INS (insulin)
Diseases named in the same sentence as INS in open-access papers (continued):
Sharing a sentence is not in itself a finding about the gene and the disease.
metabolic disorders (continued). "Administration of Akkermansia muciniphila could reverse metabolic disorders caused by HFD, such as insulin resistance, adipose tissue inflammation, and fat mass gain." (PMID 35844908, 2022). "Indeed, a decreased PBA/SBA ratio in NAFLD patients who have undergone bariatric surgery is associated with improved insulin sensitivity, indicating that an increased PBA/SBA ratio tends to induce metabolic disorder." (PMID 35670534, 2022). "DM comprises a group of metabolic diseases characterized by chronic hyperglycemia resulting from insufficient insulin secretion and/or insulin resistance in target tissues, which may lead to multi-organ dysfunction and failure." (PMID 36726817, 2022). "On the other hand, insulin exerts inhibitory effects on the gene expression of SELENOP in hepatocytes, and impaired insulin action in certain metabolic disorders might increase the expression and circulating level of SELENOP." (PMID 35883754, 2022). "Improved understanding of the tissue-specific dynamics of insulin action may provide novel insights into the progression of metabolic disease in patient populations with diverse metabolic phenotypes." (PMID 35991189, 2022). "In this review, we describe miRNAs and RBPs that control key genes involved in the insulin signaling pathway and related regulatory networks, and their impact on human metabolic diseases at the molecular level, as well as their potential use for diagnosis and future therapeutics." (PMID 35204710, 2022). "This “metabolically healthy” variant of obesity is characterized by normal insulin sensitivity and the absence of metabolic disorders, including type 2 DM." (PMID 35216477, 2022). "These transporters facilitate the transport of substrates across cell membranes, including glucose, inorganic and organic ions, small molecule drugs, xenobiotics and amino acids, and contribute to insulin signaling, glucose homeostasis and the etiology of different metabolic diseases." (PMID 35406736, 2022). "Disturbances in MSC insulin sensitivity could negatively affect adipose tissue renewal and promote the development of adipocyte hypertrophy and metabolic disorders." (PMID 36467400, 2022). "Further investigations are warranted to corroborate the anticancer action of metformin on the tumor mass toward the assessment of more comprehensive strategies halting BC progression, in particular in patients exhibiting metabolic disorders and altered insulin/IR functions." (PMID 35672854, 2022). "These beige adipose tissues may improve metabolic disorders and insulin sensitivity by consuming energy through thermogenesis, thus modulating the browning process may be a promising option for the treatment of metabolic diseases (Betz and Enerbäck, 2018)." (PMID 36703934, 2022). "What makes these obese individuals apparently protected from metabolic disease remains unclear and although there are some mouse models that exhibit a similar obese, insulin-sensitive phenotype these have been produced by genetic manipulations." (PMID 36394259, 2022). "Its role in sugar metabolism in a high-fat diet mouse model by boosting the carbohydrate metabolism, lowering the blood glucose level and insulin resistance through maintaining intestinal integrity provided a clue for the potential use of this natural polysaccharide in metabolic disorders." (PMID 35206042, 2022). "Additionally, patients receiving acupuncture and moxibustion also exhibited greater improvements in some sex hormones (LH level, LH/FSH ratio and total testosterone level) and indicators related to metabolic disorders (fasting insulin level and BMI)." (PMID 35399633, 2022). "However, subgroup analysis by metabolic status showed that irisin was significantly correlated with insulin levels in metabolic disorder subjects (summary r = 0.327, 95% CI 0.149–0.485, p < 0.05)." (PMID 36271416, 2022).
metabolic disorders (continued). "The mechanism for the phenomenon may be that metabolic disorder induced by abnormal thyroid hormone functions further increases the cellular resistance to insulin." (PMID 35641932, 2022). "Consistently, there has been evidence for AMPK-dependent GLUT4 upregulation and enhancement of cellular glucose uptake that might occur independently of the insulin signaling under metabolic disorder and oxidative stress conditions." (PMID 36232456, 2022). "The GO enrichment analysis further revealed that MLF might regulate lipid metabolism, especially lipid biosynthetic processes, oxidative stress, inflammatory responses, and insulin signaling to improve metabolic disorders and exert antidiabetic effects." (PMID 36278175, 2022). "In addition to decreased muscle mass, an increase in visceral fat and intermuscular fat can occur, resulting in metabolic disorders related to insulin resistance and inflammation of adipose tissues." (PMID 36556970, 2022). "More sensitive and non-dichotomous measures of gluco-metabolic derangement, such as insulin sensitivity index, could yield additional insight into the roles of hepatic and visceral fat in development of metabolic disease." (PMID 35966535, 2022). "The effectiveness of metformin in improving the sensitivity to insulin, and therefore in lowering insulin circulating levels, may provide a rationale to investigate the potential benefits of metformin in cancer patients affected by metabolic disorders." (PMID 35672854, 2022). "The defect of insulin secretion leads to a variety of metabolic diseases." (PMID 36111501, 2022). "However, several studies have found that long-term feeding of high concentrate diets can induce metabolic disorders which are related to abnormal hormones levels, including cortisol, leptin, and insulin." (PMID 34991199, 2022). "DM is a group of metabolic disorders due to defects in insulin secretion and/or insulin action." (PMID 35958276, 2022). "MSCs have an immunosuppressive effect and secrete a variety of cytokines, improve the microenvironment of diabetic patients, target insulin-resistant tissue, ameliorate the metabolic disorder of islet damage, and protect and regenerate islet β-cells, thereby reducing blood sugar levels." (PMID 34135959, 2021). "Fourth, metabolic data (insulin, adiponectin, controlled attenuation parameter of the FibroScan, etc) were not collected at any point during follow-up, making it difficult to understand the increasing role of metabolic disorders in this patient population." (PMID 33821807, 2021). "Both metabolic disorders represent insulin resistant states." (PMID 33479282, 2021). "This devastating metabolic disease arises when insulin-sensitive tissues such as the liver, muscle and adipose tissue become insulin resistant, eventually leading to pancreatic beta-cell failure, reduced insulin secretion, and ultimately abnormally high blood glucose levels." (PMID 33806754, 2021). "In contrast, we found that hepatic overexpression of Map2k6 reduced adiposity, and plasma glucose and insulin, indicating that liver regulation of Map2k6 may be pivotal for metabolic disease development." (PMID 33417276, 2021). "In this review, we have tried to present evidence of the possible involvement of TRPA1 channels in neuropsychiatric and metabolic disorders and a possible hint towards using TRPA1 modulators to target appetite, lipid metabolism, glucose and insulin homeostasis and inflammation associated with NPDs." (PMID 34912298, 2021). "Intracellular accumulation of lipids impairs insulin action and contributes to metabolic disorders." (PMID 34067751, 2021). "Insulin is one of the most critical hormones in the development of metabolic diseases." (PMID 33763034, 2021).
metabolic disorders (continued). "Nme7 interacts directly with several entities related to lipid handling and insulin sensitivity, including the established nodes of metabolic diseases: the mitogen-activated protein kinase kinase kinase kinase 4 (Mapk4k4) and hepatocyte nuclear factor 4 (Hnf4)." (PMID 34356103, 2021). "DM occurs due to metabolic disorders, especially when the insulin secreted by the islet cells is insufficient or the body could no longer utilize the insulin effectively, further resulting in the disorder of glucose metabolism." (PMID 34574294, 2021). "Appreciation of a combined role of Mg and insulin and, in particular, their functional interaction could provide novel prophylactic and therapeutic strategies against metabolic diseases of high-milk-producing cows in the period after calving." (PMID 34072724, 2021). "Taken together, our results provided new information on the mechanisms that might be involved in human granulosa cells exposed to high concentrations of FFA and insulin in the contexts of metabolism disorders." (PMID 34930403, 2021). "Administration of multiple daily insulin injections (70 units/day), and oral administration of 500 mg/day metformin, 15 mg/day pioglitazone, and 200 mg/day bezafibrate had proven ineffective for her metabolic disorders." (PMID 34135866, 2021). "ECHDC3 is one of the candidate genes for PW, and ECHDC3 is a kind of testis-tissue sperm-binding protein-encoded gene, and studies have shown that it was mainly related to metabolic disease and insulin sensitivity, and might affect the growth of animals." (PMID 34203505, 2021). "Dysfunctional adipose tissue (AT) may contribute to the pathology of several metabolic diseases through altered lipid metabolism, insulin resistance, and inflammation." (PMID 33917642, 2021). "However, further understanding of how HG affects insulin action using these molecules is crucial for developing future pharmaceutical and nutritional strategies to struggle with metabolic disorders like T2DM." (PMID 34299331, 2021). "Moreover, protein disulfide-isomerase (PDI) is required for optimal insulin production to maintain glucose homeostasis in metabolic diseases." (PMID 33807173, 2021). "Since decreased insulin clearance is considered a relatively upstream inducer of metabolic disease, increased insulin clearance by SGLT2i treatment could be involved, at least in part, in the mechanisms underlying those improvements." (PMID 34572340, 2021). "In terms of metabolic disorders, in addition to the body surface features of overweight and increased body fat, hematological indicators showed that serum insulin, serum NRG4, and serum C-peptide were significantly increased, and serum irisin was significantly decreased." (PMID 34427289, 2021). "The aim of the study was to evaluate the effects of 8-week Nordic walking (NW) training at maximal fat oxidation intensity (FATmax) on changes in body mass, as well as those in insulin resistance and asprosin levels among young women with visceral obesity and metabolic disorders." (PMID 34539448, 2021). "In this review, we discuss the current knowledge regarding alterations in brain glucose metabolism, studied with [18F]-FDG-PET from metabolic disorders to AD, with a special focus on how manipulation of insulin levels affects brain glucose metabolism in health and in systemic insulin resistance." (PMID 33917464, 2021). "TSP‐1 is a known regulator of insulin sensitivity and metabolic disorder." (PMID 33566451, 2021). "Further molecular and metabolic characterizations of the liver and other insulin‐sensitive tissues represent an exciting research area to better understand the effects of lupin proteins and their potential use in the management of metabolic disorders." (PMID 34026071, 2021). "This is an interesting finding because it may be protective against possible metabolic disorders by diminishing pro-inflammatory status and favoring the action of insulin." (PMID 33105758, 2020).
metabolic disorders (continued). "By inhibiting the aggregation of M1 macrophages and inhibiting the chronic inflammation of adipose tissue and liver mediated by inflammation, metabolic disorders and chronic inflammation could be improved, and the insulin sensitivity could be increased." (PMID 33551809, 2020). "Therefore, adipocyte senescence induces systemic metabolic disorders at least partially through impairing fat insulin signaling." (PMID 31980643, 2020). "It was reported that chronic adipose tissue inflammation could impair insulin sensitivity and induce lipids metabolic disorder." (PMID 32876525, 2020). "Adiponectin, an adipocyte-derived protein related to insulin sensitivity, weight gain, and anti-inflammation, has attracted great attention because of its potential role of being a biomarker to predict cardiovascular and metabolic diseases." (PMID 33551872, 2020). "The novel discovery of the fate of several DPP4+ progenitor cell populations illustrates additional metabolic pathways that may also contribute to the regulation of glucose, insulin sensitivity, and metabolic disease." (PMID 32231442, 2020). "In addition to these metabolic disorders, old mice developed adipose tissue inflammation, elevated plasma free fatty acid concentrations and presented glycolytic muscle insulin resistance in old mice." (PMID 32708537, 2020). "Omental fat from obese individuals with higher ANGPTL4 displayed signs of inflammation and meta-inflammation, i.e., apoptosis, cell stress, and matrix rearrangement markers, known to be involved in the alteration of insulin sensitivity and development of metabolic diseases." (PMID 33003532, 2020). "Skeletal muscle is thought to be the primary organ responsible for insulin-stimulated glucose tolerance; therefore, the resistant response of skeletal muscle to insulin stimulation is considered a key step in the progress of metabolic diseases." (PMID 32178449, 2020). "Apart from the decrease in lipid storage and the release of free fatty acids into the circulation, promoting thereby whole-body insulin-resistance, adipose tissue plays a crucial role in the development of metabolic diseases, due to its critical immune and endocrine functions." (PMID 32756352, 2020). "Insulin is a key regulator of both glucose and lipid homeostasis and any long term disruption in its signalling or action has significant impact on the development of metabolic disease." (PMID 32366255, 2020). "Furthermore, we found that MUAC is strongly correlated with waist circumference, lipid parameters, blood pressure, and insulin, which indicated that abnormal local fat depot is a potential screening index for identifying metabolic disorders." (PMID 32493449, 2020). "DM is a metabolic disease resulting from defects in insulin secretion and/or insulin action." (PMID 32503241, 2020). "Thus, the aim of our study was to identify infrared spectral signatures of saliva that are suitable to monitoring this metabolic disease in untreated and insulin-treated conditions." (PMID 32182246, 2020). "Also, the implication of insulin during metabolic disorders involving T2D is marked, but, the effect of BC on insulin levels has not been studied." (PMID 28790167, 2019). "DM is a metabolic disorder characterized by chronic hyperglycemia together with disturbances in the metabolism of carbohydrates, proteins and fat, which in general results from an insulin availability and need imbalance." (PMID 31658729, 2019).
metabolic disorders (continued). "As our knowledge of genetic variation impacting metabolic diseases continues to grow, clustering and other approaches will continue to refine our understanding of these critical endophenotypes, such as dysregulated insulin processing or unfavorable fat distribution." (PMID 31292748, 2019). "Therefore, our results evaluating the effect of IR on varied metabolic disorders provided the evidence base for individualized dietary and exercise recommendations on modifying insulin sensitivity to reduce progression to related metabolic diseases." (PMID 31223344, 2019). "Mechanistically, in HFD-induced metabolic disorders, the alterations of body mass, glycemia, insulin, and liver condition are all rooted to lipid overloading, which may affect either metabolic process per se or dysbiosis, or both." (PMID 31233515, 2019). "Therefore, it can be assumed that the amount of mtDNA in various types of insulin-dependent tissues, such as AT and blood cells, is an important indicator of various metabolic disorders." (PMID 30871547, 2019). "Excessive body weight and increased amount of body fat, especially in the abdominal area, is the main reason for the development of tissue resistance to insulin, while the distribution of adipose tissue seems to be of key importance in the development of metabolic disorders in ever younger persons." (PMID 31500356, 2019). "Dietary capsaicin reduces obesity-related glucose intolerance by regulating inflammatory responses and fatty acid oxidation in obese mice fed with a high-fat diet, pointing to its potential for controlling insulin sensitivity and blood glycemia in metabolic disorders." (PMID 30987128, 2019). "Crosstalk in the pathophysiological processes underpinning metabolic diseases and neurodegenerative disorders have been the subject of extensive investigation, in which insulin signaling and autophagy impairment demonstrate to be a common factor in both conditions." (PMID 31231176, 2019). "In summary, metabolic diseases affecting insulin signaling may impair the synaptic function through a plethora of molecular mechanisms targeting neurons, astrocytes, endothelial or inflammatory cells." (PMID 31417349, 2019). "In addition, improvements in several metabolic disease risk indicators, including LDL cholesterol, blood pressure, and fasting insulin were observed." (PMID 31890243, 2019). "Moreover, our findings suggest that metabolic disorders lead to an impaired glucose homeostasis and insulin sensitivity, through the downregulation of several mRNA and miRNA, which play an important role in glucose and lipid metabolism." (PMID 31151180, 2019). "T2DM is a progressive metabolic disorder classically defined by chronic hyperglycemia due to the combination of an abnormal insulin secretion by pancreatic islet β-cells and increased insulin resistance of insulin-target tissues (adipose tissue, skeletal muscle, liver, and brain)." (PMID 31072002, 2019). "Brain glucose metabolism is impaired in AD, and growing evidence supports the concept that AD is fundamentally a metabolic disease with progressive dysfunction in brain glucose utilization and responsiveness to insulin and insulin-like growth factor stimulation." (PMID 31427921, 2019). "PLA2G2A (secretory phospholipase A2 group IIA) was the most significant upregulated gene (fold change 3.9; adjusted P = 1.43E− 20), which is of particular interest to metabolic diseases in the context of atherogenesis, hepatic cholesterol metabolism and insulin sensitivity." (PMID 31664995, 2019). "Future research, using in vivo models, should evaluate if hypothalamic stimulation of this receptor may lead to the development of metabolic diseases, by affecting whole-body insulin sensitivity." (PMID 30972025, 2019).